CD38 (CD38 molecule)
Diseases named in the same sentence as CD38 in open-access papers (continued):
Sharing a sentence is not in itself a finding about the gene and the disease.
type 2 diabetes (13 papers, 2008 to 2025). "In agreement with these functional features, the presence ofanti-CD38 autoantibodies in type 2 diabetic patients was associated withsignificantly higher levels of fasting plasma C-peptide and insulin, ascompared with anti-CD38 negative subjects." (PMID 19300526, 2008). "In conclusion, our study demonstrates that CD38 deficiency improved type 2 diabetes-induced cardiomyopathy via inhibiting pyroptosis and apoptosis in vivo and in vitro, in which the underlying mechanisms were mainly related to activating Sirt3/FOXO3a signaling pathways." (PMID 37958991, 2023). "Furthermore, glucose-evoked Ca2+ signals and insulin secretion are impaired in mouse Cd38−/− pancreatic β cells, and Cd38−/− mice show glucose intolerance, and human CD38 autoantibodies and CD38 mutations have been shown to be associated with type-2 diabetes." (PMID 26152717, 2015). "Our results showed that CD38 knockout mice had decreased blood glucose and significantly improved insulin resistance under type 2 diabetes." (PMID 37958991, 2023). "Autoantibodies against CD38 in several type 2 diabetes patients also suggest an important role in the disease, however these results are under debate." (PMID 19575795, 2009). "The decreased function of the CD38 mutant may have contributed to the impairment of glucose-stimulated insulin secretion in type 2 diabetes patients." (PMID 35457121, 2022). "A total of eleven of genes were differently expressed in celiac patients compared with disease controls of which CD36, CD38, FOXP1, SELL, PPARA, PPARG, AGT previously associated with type 2 diabetes and AKAP6, NTNG1 with anorexia nervosa remained significant after correction for multiple testing." (PMID 27483138, 2016). "Our data suggest that CD38/cADPR-mediated Ca2+ signals play a key role in glucagon-induced gluconeogenesis in hepatocytes, and that the signal pathway has significant clinical implications in metabolic diseases, including type 2 diabetes." (PMID 26038839, 2015). "Loss of CD38 function is associated with impaired immune responses and metabolic disturbances, while increased CD38 surface expression is a marker of immune activation that has been linked not only to HIV, but also to B cell malignancies, solid tumors and type 2 diabetes." (PMID 23717651, 2013). "Therefore, when anti-CD38 antibodies are present in patients, glucose-induced insulin secretion could be impaired and result in type 2 diabetes." (PMID 35457121, 2022). "In contrast, the introduction of lentiviral-vector mediated delivery of human CD38 Arg140Trp (rs1800561), which had first been found in Japanese type 2 diabetic patients, failed to recover the social memory and maternal care." (PMID 35457121, 2022). "This study investigated the dysregulation of key NAD+ salvage enzymes (CD38, NAMPT, and SIRT1) across albuminuria stages in type 2 diabetes (T2D)." (PMID 41470091, 2025).
Anxiety (12 papers, 2013 to 2026). Intense feelings of nervousness, tension, or panic often arise in response to interpersonal stresses. "Interestingly, there is also a report of a slight association between the COMT met158 allele and teacher rated anxiety in autistic students which nicely fits to our finding of an increased amygdala activation in CD38 risk allele carriers also carrying the COMT met158 allele." (PMID 23554586, 2013). "The results showed that middle-aged CD157 KO mice displayed decreased locomotor activity and severe anxiety-related behavior, while middle-aged CD38 KO mice displayed reduced locomotion with less anxiety-related behavior." (PMID 33326496, 2020). "Young adult (approximately 8–12 weeks old) CD38 KO mice showed increased locomotor activity, deficits in social memory reductions in anxiety-like behavior, and impairment in parental behavior." (PMID 33326496, 2020). "Middle-aged CD38 KO mice showed less anxiety and hyperactivity than CD157 KO mice, similar to young adult CD38 KO mice." (PMID 33326496, 2020). "The broad behavioral improvements—spanning anxiety, physical function, and multiple cognitive domains—suggest that CD38 inhibition could address several aspects of aging simultaneously." (PMID 41542058, 2026). "Furthermore, CD38−/− mice showed comparable locomotive activity and anxiety level to WT controls in the open field and elevated plus maze tasks." (PMID 26856703, 2016). "However, although middle-aged male CD38 KO mice displayed anxiety-related behavior during the habituation stage, no age-associated changes were observed in middle-aged CD38 KO mice in the open field test with the non-social and social targets." (PMID 33326496, 2020). "Since homozygote met allele carriers (worriers) are more sensitive to stressors and have a higher trait anxiety, they might particularly benefit from an increased OT level as present in the A+ carriers of the CD38 gene leading to the well-known stress dampening effect of OT on the amygdala." (PMID 23554586, 2013). "This enhanced focus on neuroticism would be consistent with elevated levels of anxiety and emotional reactivity to negative events that have been seen in mice with deletion of the CD38 gene." (PMID 32116489, 2020). "Based on the activity of CD38 as an enzyme that produces the calcium-mobilizing second messenger cyclic ADP-ribose (cADPR), CD157, a sister protein of CD38, has been considered a candidate mediator for the production and release of OT and its social engagement and anti-anxiety functions." (PMID 32572044, 2020). "CD38−/− mice displayed impairments in parental retrieval behavior, social recognition, depression-like behavior and adhedonic behavior, but not in anxiety-like behavior." (PMID 29035307, 2017).
colitis (12 papers, 2015 to 2024). Inflammation of the colon. "We previously demonstrated that anti–CTLA-4/PD-1 colitis is associated with high levels of activated (HLA-DR+CD38+) memory CD8+ T cells, and lower proportions of regulatory T cells compared with UC." (PMID 34147519, 2021). "The molecular mechanisms underlying the effect of CD38 in intestinal macrophages in colitis require further research." (PMID 31179321, 2019). "Taken together, these results indicate that CD38 mice are substantially less susceptible to DSS-induced colitis." (PMID 25938500, 2015). "In a mouse model of colitis, CD38 deficiency relieves colonic inflammatory symptoms." (PMID 33860064, 2021). "First, IBD in humans and colitis in mice express CD38 in colon mucosal residents and infiltrating immune cells." (PMID 37371959, 2023). "Our results show an increase in Cd38 gene expression in the mucosal scrapings of mice undergoing DSS-induced colitis." (PMID 37744380, 2023). "CD38−/− mice have shown decreased immune cell infiltration and mild colitis symptoms upon DSS treatment." (PMID 31179321, 2019). "In the DSS-induced colitis model and T cell transport colitis model, CD38 expression gradually increased with the emergence of colitis." (PMID 31179321, 2019). "Using the NCBI GEO database, we confirmed increased CD38 mRNA expression in patients with UC and in mouse colitis models." (PMID 31179321, 2019). "Whereas wild-type mice developed severe colitis, CD38-/- mice had only mild disease following DSS-treatment." (PMID 25938500, 2015). "CD38−/− mice have milder colitis, and CD38-targeted cancer and aging therapies may also result in IBD." (PMID 37371959, 2023). "CD38 protein expression also increased in the mice with DSS-induced colitis." (PMID 31179321, 2019). "Moreover, CD38-/- mice subjected to DSS colitis only developed mild colitis as compared to WT mice." (PMID 37744380, 2023). "Moreover, Cd38-/- mice display milder colitis, suggesting that the upregulation of this molecule is pathogenic in IBD and that therapeutic modalities targeting CD38 in cancer and aging might also be relevant for this disease." (PMID 35976971, 2022). "There was an increased proportion of CD38+ “M1-like” macrophages and elevated Th17 cells in the colonic lamina propria (cLP) of Vav-Rab27A cKO mice after DSS colitis." (PMID 36214220, 2022). "To determine the role of CD38 in intestinal inflammation, we applied the dextran sulfate sodium (DSS) colitis model." (PMID 25938500, 2015). "The similar phenotype of CD38-/- and TRPM2-/- mice in the DSS colitis model further suggests that ADPR generation is central to this function of CD38." (PMID 25938500, 2015). "FK866, a small NAMPT inhibitor, reduces mucosal NAD+ and NAD+-dependent enzymes (including PARP1, SIRT6, and CD38), NF-κB pathway activation, and inflammatory cell infiltration, thereby improving DSS-induced colitis in mice and preventing inflammation-related tumors." (PMID 37371959, 2023). "We extracted data pertaining to the 3 CD8+ TRM cell populations and found that the CD8+ TRM cell population 2, comprised mostly cells from patients with PD-1 colitis, has markedly high expression of activation markers (HLADR, CD38) and checkpoint molecules (CTLA4, TIM3)." (PMID 34147519, 2021). "Mice with genetic CD38 knockout do not develop colitis when exposed to LPS." (PMID 39795876, 2024). "Although we provide evidence of a PARP-related decline in NAD+ levels during colitis, we cannot rule out the role CD38 may also play in modulating NAD+ levels during intestinal inflammation." (PMID 37744380, 2023).
Hypertension (12 papers, 2017 to 2024). The presence of chronic increased pressure in the systemic arterial system. "In the present study, we observe that CD38 deficiency significantly attenuated Ang II infusion-induced hypertension and vascular remodeling by delaying VSMC senescence." (PMID 34112762, 2021). "First, we demonstrated that CD38 deficiency alleviated Ang II-induced hypertension and vascular remodeling by inhibiting VSMC senescence." (PMID 34112762, 2021). "In conclusion, our study demonstrated that CD38 deficiency significantly alleviated Ang II-induced hypertension and vascular remodeling by inhibiting the SA-sEV-mediated senescence of VSMCs." (PMID 34112762, 2021). "Taken together, these results demonstrated that CD38 deficiency ameliorated Ang II-induced hypertension and hypertension-induced vascular remodeling." (PMID 34112762, 2021). "Therefore, we speculate that CD38 deficiency may alleviate vascular remodeling in hypertension by inhibiting VSMC senescence." (PMID 34112762, 2021). "To further reveal the role of CD38 in hypertension in vivo, we used 2 strategies, including using CD38 knockout (KO) mice and CD38 inhibitors in AngII-induced hypertensive mice." (PMID 37718359, 2023). "To further determine the potential role of endothelial CD38 in hypertension, we carried out an adeno-associated virus (AAV)-mediated endothelial CD38 knockdown experiment in vivo." (PMID 37718359, 2023). "In comparison, in our study, we aimed to assess CD38 expression in the brain in presence of hypertension using SHRSP which are a known genetic model for marked hypertension and CSVD." (PMID 35712720, 2022). "To identify changes of CD38 expression and enzymatic activity in the brain in the setting of hypertension, we utilized spontaneously hypertensive stroke-prone rats (SHRSP), an established genetic model for severe hypertension." (PMID 35712720, 2022). "Considering the importance of CD38 in lymphocytes, the effects of normal CD38-expressing lymphocytes on Ang II-induced hypertension and vascular remodeling were evaluated with a bone marrow transplantation assay." (PMID 34112762, 2021). "These cardiovascular changes were accompanied by reductions in circulating IFN-γ and IL-6 as well as activated (CD38+) and immunosenescent (CD57+CD28null) CD8+T cells, previously implicated in hypertension." (PMID 31504461, 2019). "Betamethasone, another hormone, administered antenatally in sheep model leads to increased CD38 expression and contributes to postnatal hypertension suggesting a potential augmenting effect of CD38 in peripheral vascular resistance." (PMID 29576747, 2018). "Following 14 days of Ang‐II infusion with osmotic mini‐pumps, a comparable hypertension was generated in both of CD38 knockout and wild‐type mice." (PMID 28296029, 2017). "Overall, the present study may shed new light on novel strategies in which NAD+ boosting therapy, including NMN supplement and CD38 inhibition, may turn out to be a promising therapeutic measure to treat patients with hypertension." (PMID 37718359, 2023). "Given that macrophage infiltration-related inflammation has been shown to exacerbate hypertension and vascular dysfunction, we examined whether the pro-inflammatory macrophages were involved in the IL-1β secretion and the upregulation of CD38 in ECs." (PMID 37718359, 2023). "In this study, we hypothesized that NAD+ exhaustion in endothelial cells mediated by CD38 activation contributed to the BP elevation and vascular damage in hypertension." (PMID 37718359, 2023). "However, the role of CD38 in hypertension induced vascular cognitive impairment and cerebral small vessel disease has not yet been investigated." (PMID 35712720, 2022). "It is suggested that, in SAS patients, the upregulation of Ren and Cd38 may induce hypertension, while miR-203 could play a crucial role in the regulation of such gene expressions." (PMID 34576290, 2021).
Hypertension (continued). "In the present study, the decline of the miR-203 with a common target sequence in the Ren and Cd38 mRNAs could have contributed to the worsening hypertension in the IH condition induced by the upregulation of the Ren and Cd38 mRNAs." (PMID 34576290, 2021). "Finally, CD38 expression on the endothelial cells in the brain of SHRSP may also suggest its potential role in endothelial cell dysfunction in the setting of hypertension as evident by the decreased NO and eNOS levels observed in our experiments." (PMID 35712720, 2022). "Mechanistically, we explored the effect of macrophage-endothelium interactions on CD38 and NAD+ levels in hypertension in vitro and in vivo." (PMID 37718359, 2023). "In conclusion, we show that SHRSP, a genetic model of marked hypertension and CSVD, exhibits increased CD38 expression and enzymatic activity in the brain compared to normotensive control WKY." (PMID 35712720, 2022). "Our findings suggest the potential role of CD38 in the pathogenesis of hypertension-induced CSVD and indicate the importance of future studies aiming to inhibit the enzymatic activity of CD38 to prove this role and develop future disease targeted therapeutics." (PMID 35712720, 2022). "We aimed to characterize CD38 expression and enzymatic activity in the brain of spontaneously hypertensive stroke-prone rats (SHRSP), a genetic model for hypertension and human CSVD, in comparison to age-matched normotensive Wistar Kyoto rats (WKY)." (PMID 35712720, 2022). "Moreover, the inflammation induced by macrophage infiltration plays a key role in the CD38 activation, promoting NAD+ deprivation in hypertension." (PMID 37718359, 2023). "The present study demonstrated for the first time that endothelial CD38 activation and subsequently accelerated NAD+ degradation due to enhanced macrophage-derived IL-1β production was responsible for BP elevation and vascular damage in hypertension." (PMID 37718359, 2023). "Therefore, in this work, we characterize CD38 expression and enzymatic activity in the brain of SHRSP, a genetic model of severe hypertension and CSVD, compared to age-matched normotensive Wistar-Kyoto (WKY) rats." (PMID 35712720, 2022). "However, to date, it is not known whether CD38 enzymatic activity is increased in the setting of hypertension induced CSVD and oxidative stress." (PMID 35712720, 2022). "Taken together, IH upregulates the mRNA levels of Ren and Cd38 in JG cells via the downregulation of miR-203-mediated mRNA degradation and the mRNA levels of DBH and PNMT in neuroblastoma cells via the inhibition of miR-375-mediated mRNA degradation, which may contribute to hypertension." (PMID 36361741, 2022).
Thrombocytopenia (12 papers, 2018 to 2025). A reduction in the number of circulating thrombocytes. "Meta-analyses confirmed that anti-CD38 therapies significantly increase the risk of neutropenia and thrombocytopenia." (PMID 40786241, 2025). "Similarly, the decreased CD38+HSPCs entropy level was associated with specific features of MDS such as deeper thrombocytopenia and neutropenia." (PMID 38575672, 2024). "Hematologic toxicities, particularly neutropenia and thrombocytopenia, are among the most frequent AEs in patients undergoing CD38-based quadruplet therapy for NDMM." (PMID 40271095, 2025). "There was a significant increase in hematological adverse events, such as neutropenia (RR 1.41; 95% CI 1.26–1.58; p < 0.01) and thrombocytopenia (RR 1.14; 95% CI 1.02–1.27; p = 0.02), in the group treated with anti-CD38 monoclonal antibody." (PMID 38672988, 2024). "Although debatable, thrombocytopenia causes a physiologic compensatory secretion of thrombopoietin that seems to correlate with other prognostic biomarkers including IGHV mutation status, ZAP 70 and CD38." (PMID 30450231, 2018).
acute leukemia (11 papers, 2011 to 2025). A clonal (malignant) hematopoietic disorder with an acute onset, affecting the bone marrow and the peripheral blood. "Flow cytometry of bone marrow biopsy revealed an immature (blast) cell population expressing CD5, CD34, and CD38, highly suggestive of acute leukemia, particularly AML, given the co-expression of CD13 and CD33 found in peripheral blood." (PMID 40978971, 2025). "Based on the high expression of CD38 on the surface of acute leukemia cells, CD38 mAb has also gradually been applied for the treatment of acute leukemia." (PMID 36313735, 2022). "Acute leukemias are due to an anomaly of the stem cell characterized among other things by the expression of CD34+ CD38− surface markers." (PMID 23667721, 2013). "We report a case of acute leukemia CD34+/-HLADR+CD7+CD38+cyCD3- in which a diagnosis of AUL was considered." (PMID 22937302, 2011). "The latest analyses show that CD38 is a promising therapeutic antigen for acute leukemia." (PMID 33292550, 2020). "Additional studies are needed to elucidate the efficacy and safety of CD38-targeted therapies, such as bispecific antibodies, trispecific antibodies, ADCs, multitarget CARTs, and CAR-NK cell therapy, in acute leukemia." (PMID 36313735, 2022). "Herein, this review focuses on targeting CD38 therapies in ALL and AML, which demonstrate sound antileukemic effects in acute leukemia and are expected to become effective treatment methods." (PMID 36313735, 2022). "Daratumumab, a recombinant anti-human CD38 monoclonal antibody approved by the FDA for the treatment of myeloma, has also been suggested to be effective in the treatment of acute leukemia." (PMID 33292550, 2020).